SDC1 (syndecan 1)
Diseases named in the same sentence as SDC1 in open-access papers (continued):
Sharing a sentence is not in itself a finding about the gene and the disease.
colorectal cancer (continued). "Additionally, low expression of Sdc-1 corresponded with poor prognosis in colorectal cancer patients." (PMID 33330449, 2020). "Interestingly, another large-scale secretome study to find cancer biomarkers also observed syndecan-1 in the extracellular media in three different types of cancer cell lines originated from oral cancer, colorectal carcinoma and lung cancer." (PMID 22905270, 2012). "The only correlation between syndecan-1 and clinicopathologic factors was found in adenoid cystic carcinoma, where both intensity and percentage were higher in the stroma of male patients, which was similar to the findings of another study in colorectal carcinoma." (PMID 31540870, 2021). "Given the link between chronic inflammation and colorectal cancer, along with the changes in Sdc1 expression that were reported in both inflammatory and malignant disorders, we hypothesized that Sdc1 null mice would show altered susceptibility to chronic colitis-associated cancer." (PMID 28350804, 2017). "Interestingly, SDC1 is downregulated in various malignances, such as colorectal cancer, indicating that this HSPG may serve as a prognostic marker in a cancer-type-specific manner." (PMID 23327652, 2013). "However, the prognostic relevance of changes in syndecan-1 expression in colorectal carcinoma remains unclear from the published studies." (PMID 18590537, 2008). "SDC1 expression is decreased in colorectal cancer (CRC) tissue, but the relationship between prognosis and SDC1 expression in CRC patients is controversial." (PMID 31182980, 2019). "Moreover, HPSE-induced SDC-1 shedding indirectly activates EGFR signaling, as soluble SDC-1 binds HB-EGF through intact HS chains, stimulating EGFR pathways and promoting chemotherapy resistance in colorectal cancer." (PMID 41301515, 2025). "Several studies linked Sdc-1 to colon tumorigenesis, however, unlike its involvement in inflammation, the role of Sdc-1 in colorectal cancer remains less unequivocal and, in light of the recent reports, is most likely context-specific." (PMID 28350804, 2017). "The authors also reported that syndecan-1 expression does not have prognostic value in colorectal carcinoma patients." (PMID 26869927, 2016).
pancreatic cancer (36 papers, 2011 to 2026). "In pancreatic cancer cells, lipid synthesis potentiates expression of macropinocytosis-associated genes, including SDC1, DNM2, via the ZIP4 (solute carrier family 39 member 4) pathway." (PMID 40408281, 2025). "Syndecan-2 also plays a significant role in pancreatic cancer, working as an invasive-associated gene that, as well as syndecan-1, cooperates with KRas to induce the invasive phenotype." (PMID 33669066, 2021). "SDC-1 shedding is associated with increased mitogenic activity and invasive potential of pancreatic cancer cells, whereas shedding of SDC4 in human endothelial cells promotes wound healing, angiogenesis, and inflammation." (PMID 32916872, 2020). "Since the MMP‐7‐induced shedding of SDC1 ectodomain was previously observed in cultured pancreatic cancer cell lines, it is possible that the increased serum SDC1 level in our cohort was related to MMP‐7." (PMID 39263943, 2024). "Mechanism studies revealed that the SDC1-LB-MSN-GEM/HNK induced apoptosis of BxPC-3 pancreatic cancer cells by regulating the mitochondrial apoptosis pathway, as evidenced by decreasing MMP and ATP and increasing the level of ROS." (PMID 38338418, 2024). "We established a prognostic model based on SDC1/TUBAC/SEL1L with favorable prediction performance for pancreatic cancer." (PMID 38048216, 2023). "A comparison of SEL1L/TUBA1C/SDC1 mRNA expression levels in various pancreatic cancer cell lines using the Cancer Cell Line Encyclopedia (CCLE) database showed that most pancreatic cancer cells expressed less SEL1L than SDC1 or TUBA1C." (PMID 38048216, 2023). "Nevertheless, SDC1 levels are solely elevated in pancreatic cancer (the only gastrointestinal malignancy) which speeds up tumor growth." (PMID 38048216, 2023). "High expression of SDC1 in TCGA-pancreatic cancer cohort resulted in 269 upregulated genes and 85 downregulated genes." (PMID 38048216, 2023). "The results showed that with the extension of inoculation time of pancreatic cancer cells, the expression levels of SDC1 and ITGA2 in tumor tissues also increased." (PMID 37907515, 2023). "Immune infiltration data from the high- and low-expression SEL1L, TUBA1C, and SDC1 pancreatic cancer groups were gathered using CIBERSORT algorithms." (PMID 38048216, 2023). "The SEL1L/TUBA1C/SDC1 mRNA expression levels were compared in normal and pancreatic cancer tissues using TCGA." (PMID 38048216, 2023). "Increased levels of heparanase (HPA) in pancreatic cancer increase metastatic potential by facilitating shedding of SDC1 as well as activation of the PI3K/AKT pathway and the epithelial-to-mesenchymal transition." (PMID 35522218, 2022). "SDC are often upregulated in gastric and colon cancers, but Syndecan-1 (SDC1) is upregulated only in pancreatic cancer, where it correlates with invasion of cancer and a poor prognosis." (PMID 35522218, 2022). "More precisely this has been shown for GPC1 in pancreatic cancer cells, where syndecan-1 and GPC1 are both required for FGF2-growth factor response leading to metastasis and shedding of GPC1 cannot be compensated for by higher levels of SDC1." (PMID 33742285, 2021). "In particular, SDC1 is also reported to facilitate tumor invasion via stimulating the EMT pathway in pancreatic cancer cells." (PMID 34987579, 2021). "Pancreatic cancer tissues from 42 patients showed that expression of miR−494 was downregulated and that of SDC1 upregulated." (PMID 34249755, 2021). "The authors presented that the FGF2-growth factor-induced shedding of syndecan-1 from the cell membrane makes the mitogenic response of pancreatic cancer cells glypican-1 dependent, which in turn cannot be compensated for by syndecan-1." (PMID 33742285, 2021). "There is evidence for the post-transcriptional regulation of syndecan-1 expression in, for example, pancreatic cancer and peritoneal macrophages." (PMID 29940912, 2018).
pancreatic cancer (continued). "Future studies should explore the ability of Syndecan-1 liposomes to preferentially release drugs at the tumor site and compare their effectiveness to current treatments for pancreatic cancer." (PMID 26627455, 2015). "By targeting the liposome with Syndecan-1, this nanovehicle has potential as a targeted theranostic nanoparticle for both drug and contrast agent delivery to pancreatic tumors." (PMID 26627455, 2015). "Post-transcriptional regulation of syndecan-1 expression has been indicated previously, for example in pancreatic cancer and peritoneal macrophages." (PMID 26482785, 2015). "The Syndecan-1 liposomes demonstrated tumor specificity in orthotopic pancreatic cancer as observed using multispectral optoacoustic tomography with reduced kidney and liver uptake." (PMID 26627455, 2015). "In pancreatic cancer, SDC1 as a critical mediator of micropinocytosis to mediated the tumor growth." (PMID 41364407, 2025). "Thus, SDC1 is an appropriate ligand for developing a targeting LB-MSN nanoparticle drug delivery system for improving targeted therapy of stromal abundant pancreatic cancer through SDC1/IGF1R receptor-mediated endocytosis." (PMID 38338418, 2024). "Additionally, pancreatic cancer cells expressing SDC1 can interact with T cells expressing CCL5 in the TME, promoting tumor migration, and thereby providing a potential target for immunotherapy in pancreatic cancer." (PMID 39238647, 2024). "In addition, one study reveals that SDC1 is a critical mediator of micropinocytosis and tumor growth and is a potential target in pancreatic cancer." (PMID 38002057, 2023). "Additionally, we compared the levels of SEL1L/TUBA1C/SDC1 expression in normal and pancreatic cancer tissues using the Human Protein Atlas (HPA) database." (PMID 38048216, 2023). "Serum SDC1 is a promising new biomarker for patients with pancreatic cancer." (PMID 38048216, 2023). "In pancreatic cancer, SDC1 regulates micropinocytosis to enhance tumor growth." (PMID 35037689, 2022). "Thus, this new study reveals that syndecan-1 plays a crucial role in macropinocytosis in KRAS-driven pancreatic cancer." (PMID 33669066, 2021). "A recent integrative bioinformatic study concerned with gene expression profiling showed that SDC1 is a differentially expressed gene (DEG) in pancreatic cancer: 138 common DEGs were identified, 93 of which were up-regulated and 45 down-regulated in pancreatic carcinoma." (PMID 34249755, 2021). "The authors also reported this observation in pancreatic cancer cells as well, indicating that drug-induced shedding of syndecan-1 might occur in many cancer types." (PMID 32983743, 2020). "It has previously been observed that SDC1 expression may play an important role in the pathobiology of pancreatic cancer cell, which is different from that in other gastrointestinal cancers." (PMID 31412643, 2019). "This indicated that SDC1 might be a possible therapeutic target for pancreatic cancer." (PMID 38048216, 2023). "Our results indicate that SDC1 may be a therapeutic target for the treatment of pancreatic cancer." (PMID 38048216, 2023). "However, the fact that HPA, FGF2, and MMP7 are all upregulated in PDAC tissue samples makes it reasonable to assume that syndecan-1 shedding could also be happening during pancreatic cancer progression." (PMID 33669066, 2021). "Notably, while the expression level of SDC1 was higher in pancreatic cancer samples than normal, survival analysis on separate hub genes revealed that the survival probability was not obvious between the high expression of SDC1 and the medium/low expression group." (PMID 31412643, 2019). "SDC1-LB-MSN-GEM/HNK combined advantages of both GEM and HNK simultaneously targeted and eliminated pancreatic cancerous and cancer-associated stromal cells under the help of nanoparticles carrier may provide a new strategy for efficacious treatment of pancreatic cancer." (PMID 38338418, 2024).
pancreatic cancer (continued). "TCGA-pancreatic cancer data were classified according to NRG expression levels, SEL1L, TUBA1C, and SDC1, and each group was analyzed using GO and KEGG." (PMID 38048216, 2023). "We identified 12 GRGs differently expressed in pancreatic cancer and selected three genes (SEL1L, TUBA1C, and SDC1) to build a prognostic model." (PMID 38048216, 2023). "The results showed that after inhibiting the expression of SDC1 and ITGA2, the EMT process of pancreatic cancer cell lines was inhibited; this was manifested by an increased expression of E-cadherin and decreased expression of N-cadherin, Snail, and Twist." (PMID 37907515, 2023). "Pancreatic cancer samples had a higher expression of TUBA1C and SDC1 compared with the standard samples, while SEL1L expression was lower in vitro and in vivo." (PMID 38048216, 2023). "The HPA/syndecan-1 axis promotes the upregulation of FGF2, which in turn activates the PI3K/Akt pathway and EMT in cultured pancreatic cancer cell lines." (PMID 33669066, 2021). "In pancreatic cancer, serum SDC1 has prognostic value in early-stage patients but not in advanced cases." (PMID 41364407, 2025). "Syndecan-1 (SDC1) modified lipid bilayer (LB)-coated mesoporous silica nanoparticles (MSN) to co-deliver gemcitabine (GEM) and honokiol (HNK) were prepared for the targeting treatment of pancreatic cancer." (PMID 38338418, 2024). "We identified three GRGs closely related to pancreatic cancer: SEL1L, TUBA1C, and SDC1." (PMID 38048216, 2023). "Considering that shed SDC-1 promotes the EMT, high levels of shed SDC-1 were found to upregulate expression of EMT-TFs including ZEB1, Snail1 and Snail2 in breast and pancreatic cancer models to induce expression of the stemness factors SOX2, BMI1, and OCT4, thus facilitating chemoresistance." (PMID 35118073, 2021). "SDC1, SDC2 and SDC3 have been described to have a role in pancreatic cancer." (PMID 34249755, 2021). "Syndecan-1 (CD138) was evaluated as a target for bimodal NIRF imaging and multispectral optoacoustic tomography (MSOT, also known as photoacoustic imaging) in an orthotopic in vivo model of pancreatic cancer." (PMID 33371487, 2020). "The shedding of SDC1 serves an important role in the regulation of FGF2 signaling activation of the PI3K/Akt pathway that promotes epithelial-mesenchymal transition, invasion, and metastasis of pancreatic cancer cells." (PMID 32916872, 2020).
glioma (33 papers, 2014 to 2025). A benign or malignant brain and spinal cord tumor that arises from glial cells (astrocytes, oligodendrocytes, ependymal cells). "The results show that SDC1 is associated with the immune infiltration of glioma in the TME, especially activated CD4+T cells and CD8+T cells." (PMID 35669186, 2022). "Our previous research shows that the expression of SDC1 in human glioma is associated with advanced tumor progression and poor prognosis, and SDC1 knockdown inhibits glioma cell proliferation and invasion by deregulation of c-src/FAK related signal pathway." (PMID 35669186, 2022). "Elevated SDC1 expression in glioma was closely associated with increases in tumor progression and shorter survival." (PMID 28422726, 2017). "To explore the mechanisms underlying the SDC1 knockdown-induced inhibition of progression in glioma, we examined the activation of c-src/FAK complexes, which are important for focal adhesion in glioma cells." (PMID 28422726, 2017). "In summary, we found that high SDC1 expression in human glioma was strongly associated with more advanced tumor stages and shorter survival." (PMID 28422726, 2017). "Recent studies have shown that increased syndecan-1 (SDC1) expression in human glioma is associated with higher tumor grades and poor prognoses, but its oncogenic functions and the underlying molecular mechanisms remain unknown." (PMID 28422726, 2017). "Because glioma cells express predominantly the αvand β1 subunits of integrin and SDC1 can interact with bothof these submits, SDC1 knockdown might inhibit integrin-mediated signaling by deregulating c-src/FAK-associated signaling pathways in glioma cells." (PMID 28422726, 2017). "Our study proposed, for the first time, that SPP1/HMOX1 contributeso the activation of the PI3K/AKT, JAK–STAT and syndecan 1 signalling pathways, thereby maintaining the motility and malignancy of glioma cells." (PMID 40495644, 2025). "It has been suggested that the overexpression of Syndecan-1 in the glioma microenvironment induces tumor invasion through the upregulation of thrombospondin-1." (PMID 36980765, 2023). "Particularly, Syndecan-1 is overexpressed in almost all glioma cell lines studied and is poorly expressed in normal specimens." (PMID 36980765, 2023). "Another study confirmed that SDC1 knockdown inhibits glioma cell proliferation and invasion by deregulating a c-src/FAK-associated signaling pathway." (PMID 35432485, 2022). "Our previous research shows that SDC1 expression in human glioma correlates with advanced tumor progression and poor prognosis, and SDC1 knockdown inhibits glioma cell proliferation and invasion by deregulating a c-src/FAK-associated signaling pathway." (PMID 35669186, 2022). "The best homogeneity between tumor samples in the high and low expression of SDC1 of glioma samples is shown in the TCGA data sets." (PMID 35669186, 2022). "To further study the function of SDC1 in the glioma microenvironment, we analyzed the possibility of SDC1 related to immunity at the transcriptome level in different databases and searched for the possible molecular and signaling pathway." (PMID 35669186, 2022). "In future studies, we will experiment with cells and animals to verify and further explore upstream and downstream interactions of SDC1 in glioma." (PMID 35669186, 2022). "SDC1 was shown to discriminate between high-grade glioblastoma multiforme and low-grade glioma, and therefore, with the potential to improve the management of brain tumour patients that present high risk of surgery-associated complications." (PMID 33494442, 2021). "Heparan sulfate and chondroitin sulfate-bearing syndecan-1 has been identified as a potential plasma EV-based marker of glioma." (PMID 32842648, 2020). "In this study, SDC1 expression was analyzed in TCGA glioma samples, which included both low-grade glioma (LGG) and GBM datasets, and in the NCBI-GEO GSE4290 dataset." (PMID 28422726, 2017).